BMPR2 (bone morphogenetic protein receptor type 2)
Diseases named in the same sentence as BMPR2 in open-access papers (continued):
Sharing a sentence is not in itself a finding about the gene and the disease.
colorectal polyps (1 paper, 2025). "Regarding BMPR2, loss-of-function mutations have been associated with increased susceptibility to proliferative intestinal disorders such as colorectal polyps." (PMID 40863222, 2025).
diabetes (1 paper, 2014). "While more severe fibrosis following CP induction was observed in BMPR2 deficient mice versus their wild-type counterparts, neither persistent endocrine dysfunction nor overt diabetes was observed in either group." (PMID 24586530, 2014).
empty sella syndrome (1 paper, 2024). Empty sella syndrome (ESS) is a condition that involves the sella turcica, a bony structure at the base of the brain that protects the pituitary gland. "We report to you a case of a 32-year-old female with a rare presentation of a non-BMPR2 mutation heritable PAH complicated with empty sella syndrome and panhypopituitarism." (PMID 38524058, 2024).
epilepsy (1 paper, 2015). A brain disorder characterized by episodes of abnormally increased neuronal discharge resulting in transient episodes of sensory or motor neurological dysfunction, or psychic dysfunction.
fibrodysplasia ossificans progressiva (1 paper, 2019). Fibrodysplasia ossificans progressiva (FOP) is a severely disabling heritable disorder of connective tissue characterized by congenital malformations of the great toes and progressive heterotopic ossification that forms qualitatively normal bone in characteristic extraskeletal sites. "For example, the fibrodysplasia ossificans progressiva (FOP)-causing mutation in ALK2 results in a hypersensitive receptor, still requiring BMPR2 within the functional receptor complex." (PMID 31826007, 2019).
fibrosis (1 paper, 2014). the formation of excess fibrous connective tissue in an organ or tissue in a reparative or reactive process. "Furthermore, more severe pancreatic fibrosis and activated PSCs were observed in BMPR2+/− mice." (PMID 24586530, 2014).
fibrous dysplasia (1 paper, 2012). A genetic, non-inheritable disorder caused by osteoblastic differentiation defects that result in the replacement of bone marrow and trabecular bone by fibrous stroma and immature bone. "Fibrous dysplasia and non-fibrous dysplasia subjects could be clearly separated by differences in the expression of BMP2, BMP4, BMPR1A, BMPR2, and other members of the BMP pathway." (PMID 23230423, 2012).
glioma (1 paper, 2020). A benign or malignant brain and spinal cord tumor that arises from glial cells (astrocytes, oligodendrocytes, ependymal cells). "A new glioma grade (HB grade) based on histopathology and BMP2 expression can predict the prognosis of glioma patients, with BMPR1B and BMPR2 expression indicating a different prognosis in different types of gliomas." (PMID 33116227, 2020).
Graves disease (1 paper, 2018). Graves' disease is an autoimmune disorder that leads to overactivity of the thyroid gland (hyperthyroidism).It is caused by an abnormal immune system response that causes the thyroid gland to produce too much thyroid hormones. "In this study, we analysed the possible influence of the c.419‐43delT BMPR2 variant in patients with Graves’ disease (GD), in a molecular basis, focusing our efforts on possible alterations in the mRNA processing and synthesis." (PMID 29266775, 2018).
head and neck cancer (1 paper, 2023). A primary or metastatic malignant neoplasm affecting the head and neck. "BMPR with a high interaction score has not been studied in head and neck cancer, and there is a significant difference in the expression of BMPR2 between cancer tissues in the epithelial cell group and adjacent tissues." (PMID 36460803, 2023).
Hemoptysis (1 paper, 2013). Coughing up (expectoration) of blood or blood-streaked sputum from the larynx, trachea, bronchi, or lungs. "Whether bronchial artery hypertrophy (and perhaps, development of hemoptysis) in BMPR2 mutated patients, may result from loss of function of the BMPR2 gene or simply reflects a greater disease severity remains to be determined." (PMID 24194909, 2013).
hereditary spastic paraplegia (1 paper, 2021). Hereditary spastic paraplegias (HSP) comprise a genetically and clinically heterogeneous group of neurodegenerative disorders characterized by progressive spasticity and hyperreflexia of the lower limbs. "In hereditary spastic paraplegia (HSP) and Huntington’s disease there are mutations in BMPR2 trafficking proteins preventing BMPR2 transport to the lysosome for degradation." (PMID 34563224, 2021).
hyperandrogenism (1 paper, 2023). Excessive secretion of androgens from the adrenal glands or gonads. "Similarly, alteration of BMPR2 gene expression can lead to a polycystic ovary in mice without hyperandrogenism." (PMID 36982971, 2023).
hypopharyngeal carcinoma (1 paper, 2023). Carcinoma, predominantly squamous cell, arising from the epithelial cells of the hypopharynx. "On this basis, we found and verified that the BMPR2 gene promotes tumorigenesis and migration of hypopharyngeal carcinoma." (PMID 36460803, 2023). "Altogether, the results of the functional assays and the analysis of clinical data from TCGA allows to draw the conclusion that BMPR2 can promote the growth and metastasis of hypopharyngeal carcinoma." (PMID 36460803, 2023). "In general, reducing the expression of the BMPR2 gene can negatively regulate the proliferation and migration capacity of hypopharyngeal cancer cells." (PMID 36460803, 2023). "Overall, the single-cell perspective revealed complex crosstalk in hypopharyngeal cancer, in which BMPR2 promotes its proliferation and migration, providing a rationale for further study and treatment of this carcinoma." (PMID 36460803, 2023). "Subsequently, through the analysis of TCGA clinical information analysis and cell proliferation and migration experiments, we confirmed that the gene plays a key role in hypopharyngeal carcinogenesis, and then concluded that BMPR2 promotes hypopharyngeal carcinoma metastasis and progression." (PMID 36460803, 2023). "Therefore, BMPR2 is a potential key gene involved in the progression of hypopharyngeal carcinoma and deserves further analysis and verification regarding the function of this gene." (PMID 36460803, 2023). "Furthermore, our analysis defined the gene BMPR2 as a potential clinical target and further confirmed that it acts as an oncogene to promote the proliferation and migration of hypopharyngeal cancer cells at the cellular level." (PMID 36460803, 2023). "Additionally, we downloaded and analyzed the GSE117558 miRNA sequencing dataset of hypopharyngeal carcinoma and related survival data from the GEO database and intersected significantly different miRNAs with conservative miRNAs upstream of BMPR2 predicted by Targetscan." (PMID 36460803, 2023). "The results of the cell proliferation assay indicated that the proliferation of hypopharyngeal cancer cells with BMPR2 knockdown was significantly lower than in the negative control group." (PMID 36460803, 2023).
intrauterine growth restriction (1 paper, 2014). "Of the many BMP ligands and receptors, Bmp2, Bmpr2 and Acvr1 have been previously shown to play important roles in endometrial function, with both early implantation (Bmp2 and Acvr1) and mid-gestational (Bmpr2) defects, some reminiscent of human intrauterine growth restriction." (PMID 24945252, 2014).
latent infection (1 paper, 2021). "Taken together, these data suggest that the presence of BMPR2 is required for a latent infection to be established, as it prevents the infected cells from decreasing YY1 in response to the latency-associated increase in TGFbeta." (PMID 34061599, 2021). "Taken together, these data are consistent with the view that in order to support a latent infection, BMPR2 is required in order to express inhibitory SMAD6, which then prevents TGFbeta receptor signaling." (PMID 34061599, 2021). "Therefore, we analyzed levels of hsa-miR-29a in BMPR2 KO-iPSCs and WT-iPSCs during latent infection." (PMID 34061599, 2021). "In this study, using genetic and pharmacological methods, including an iPSC model of HCMV latency, we identified bone morphogenetic protein receptor type 2 (BMPR2) as having a critical role in the maintenance of HCMV latent infection by modulating TGFbeta signaling." (PMID 34061599, 2021). "Given that removing BMPR2 from iPSCs causes them to respond to levels of TGFbeta that are routinely observed in supernatants of latently infected iPSCs, and that it results in reduced levels of YY1, we next tested whether BMPR2 KO-iPSCs are able to establish and maintain latent infection." (PMID 34061599, 2021). "Here, we show that with HCMV, cells cannot establish a latent infection in the absence of BMPR2 and that this is due to the inability of these cells to be refractory to the presence of cellular TGFbeta, which is known to be induced during latent infection." (PMID 34061599, 2021). "Additionally, in cells in which BMPR2 was inhibited either by gene editing or biochemically (using LDN), additional blocking of TGFbetaR by SD208 rescued the ability of these BMPR2 signaling-inhibited cells to establish a latent infection." (PMID 34061599, 2021).
liver fibrosis (1 paper, 2025). "Additionally, BMPR2/ALK3 heterodimer was essential for GDF10 to inhibit liver fibrosis." (PMID 40125634, 2025). "This study identifies autocrine GDF10 activates BMPR2/ALK3‐SMAD1/5/8‐SMAD7 pathway to counteract the TGF‐β‐SMAD2/3 pathway in HSCs, thereby inhibiting HSC activation and preventing liver fibrosis." (PMID 40125634, 2025). "In summary, autocrine GDF10 activates BMPR2/ALK3‐SMAD1/5/8‐SMAD7 pathway to counteract the TGF‐β‐SMAD2/3 pathway in HSCs, thereby inhibiting HSC activation and preventing liver fibrosis." (PMID 40125634, 2025).
metastatic prostate carcinoma (1 paper, 2017). A carcinoma that arises from the prostate gland and has spread to other anatomic sites. "Recent studies found a tendency towards lower BMPR2 level in metastatic prostate cancer than that in localized prostate cancer." (PMID 28938584, 2017).
myelofibrosis (1 paper, 2018). A partial or complete replacement of the bone marrow stroma by fibrous tissue. "In primary myelofibrosis, BMPR2 is similarly downregulated in circulating CD34+ cells." (PMID 30149506, 2018). "Notably, relative to patients with secondary myelofibrosis (MF) or healthy controls, patients with idiopathic MF have reduced platelet and granulocyte BMPR2 mRNA with elevated mononuclear BMPR2 mRNA." (PMID 30149506, 2018).
myeloid leukemia (1 paper, 2014). A clonal proliferation of myeloid cells and their precursors in the bone marrow, peripheral blood, and spleen. "Meanwhile, the expression levels of BMPR2, EP300, and TNFAIP3 mRNA in myeloid leukemia cells were significantly lower than those of healthy people." (PMID 25364581, 2014). "The expression levels of BMPR2, EP300, and TNFAIP3 mRNA in cell lines from myeloid leukemia were significantly lower than those in the cells from the healthy control (P<0.05)." (PMID 25364581, 2014). "The relative expression levels of BMPR2, EP300, and TNFAIP3 mRNA in cell lines from myeloid leukemia were significantly lower than those in the cells from the healthy people (P<0.05)." (PMID 25364581, 2014). "The expression levels of BMPR2, EP300, and TNFAIP3 mRNA in B-lymphoma cells were significantly higher than those of the myeloid leukemia cells (P<0.05)." (PMID 25364581, 2014). "Results indicate that the expression levels of BMPR2, EP300, and TNFAIP3 mRNA in myeloid leukemia cell lines were significantly lower than those of healthy people or B-malignant cell lines." (PMID 25364581, 2014). "In this study, quantitative reverse transcription polymerase chain reaction (qRT-PCR) was used to analyze the expression levels of BMPR2, EP300, TGFβ2, and TNFAIPI3 in B-lymphoma and myeloid leukemia cell lines." (PMID 25364581, 2014). "The median quantities of BMPR2, EP300, and TNFAIP3 expression in the myeloid leukemia cell lines are 0.10%, 0.56%, and 0.34%, respectively." (PMID 25364581, 2014). "Although BMPR2, EP300, TGFβ2, and TNFAIPI3 have been studied in lymphoma or leukemia, no report has compared the expression of the four genes among B-lymphoma cells, the healthy control, and myeloid leukemia." (PMID 25364581, 2014). "BMPR2, EP300, and TNFAIP3 mRNA have been observed to be almost absent in myeloid leukemia cell lines." (PMID 25364581, 2014).
myocardial infarction (1 paper, 2025). Gross necrosis of the myocardium, as a result of interruption of the blood supply to the area, as in coronary thrombosis. "Elevated monocyte ICAM1 has been linked to inflammation and vascular injury resulting from myocardial infarction, and elevated ICAM1 in the BMPR2 mutant PAH monocyte had a much greater impact on enhanced adhesion and transendothelial migration than PAH EC." (PMID 40234964, 2025).
Oligodontia (1 paper, 2023). The absence of six or more teeth from the normal series by a failure to develop. "In conclusion, we provide the first genetic evidence of the etiological correlation between BMPR2 heterozygous variants and nonsyndromic oligodontia." (PMID 36675162, 2023). "To further explore the pathogenic mechanism of heterozygous BMPR2 variants associated with oligodontia, we simulated the BMPR2 heterozygosity found in oligodontia in vitro and confirmed the successful expression of heterozygotes via Western blotting." (PMID 36675162, 2023). "In the present study, we identified a novel heterozygous variant (c.814C > T; p.Arg272Cys) of BMPR2 in a family with nonsyndromic oligodontia by performing whole-exome sequencing." (PMID 36675162, 2023). "In this study, we identified three novel BMPR2 missense variants, p.Arg272Cys, p.Val348Ile, and p.Lys477Glu, in an autosomal dominant family and two isolated patients with nonsyndromic oligodontia." (PMID 36675162, 2023). "Our results indicate that BMPR2 can be considered a novel pathogenic gene of nonsyndromic oligodontia." (PMID 36675162, 2023). "To further explore the prevalence of the BMPR2 variants in unrelated individuals with oligodontia and evaluate whether BMPR2 is a candidate pathogenic gene, we screened the whole coding region of BMPR2 in a cohort of 130 individuals with undefined etiology." (PMID 36675162, 2023). "Two individuals were found to carry two additional novel BMPR2 variants, indicating that the detection rate of BMPR2 in nonsyndromic oligodontia was 1.5%." (PMID 36675162, 2023). "Our findings broaden the genetic spectrum of oligodontia and provide clinical and genetic evidence supporting the importance of BMPR2 in nonsyndromic oligodontia." (PMID 36675162, 2023). "Our study is the first to link the genetic importance of BMPR2 to human oligodontia." (PMID 36675162, 2023). "Although previous studies demonstrated the association of BMPR2 variants with PAH, all the individuals with BMPR2 variants in our study presented oligodontia with no PAH-associated symptoms." (PMID 36675162, 2023). "However, the genetic significance of BMPR2 in oligodontia has not been previously reported." (PMID 36675162, 2023).
ovarian diseases (1 paper, 2023). "In addition, the deregulation of GSTM2 (DNA damage), SFRP1, and BMPR2 (involved in folliculogenesis) has been described in ovarian diseases." (PMID 36982971, 2023). "Some DEGs in F1 ovaries are related to reproductive/ovarian diseases, particularly POI (as Wt1, Bmpr2, Zp1, Zp2) and PCOS (as Tcf21, Fst, Bmpr2)." (PMID 36982971, 2023).
Premature ovarian insufficiency (1 paper, 2023). Amenorrhea due to loss of ovarian function before the age of 40. "Among these genes, ZP1, WT1, and BMPR2 are premature ovarian insufficiency (POI) genes in humans." (PMID 36982971, 2023).
Pulmonary hypoplasia (1 paper, 2016). "Dysfunction of BMPR2 and downstream signaling have been shown to disturb the crucial balance of proliferation of smooth muscle cells, contributing to the pathogenesis of human and experimental pulmonary hypoplasia." (PMID 26744354, 2016).
rectal carcinoma (1 paper, 2017). A malignant epithelial neoplasm that arises from the rectum and invades through the muscularis mucosa into the submucosa. "Additionally, BMPR2 rs2228545 and RUNX2 rs2819854 genotypes were associated with differential miRNA expression between rectal carcinoma and normal rectal mucosa." (PMID 28061442, 2017).
systemic lupus erythematosus (1 paper, 2023). An autoimmune multi-organ disease typically associated with vasculopathy and autoantibody production. "In systemic lupus erythematosus patients with PAH, lipopolysaccharide (LPS)-induced pyroptosis contributes to defective BMPRII (bone morphogenetic protein receptor type 2) signaling, which has a central role in PAH pathogenesis." (PMID 36834742, 2023).